CYP2A13 (cytochrome P450 family 2 subfamily A member 13)
Description:
Exhibits a coumarin 7-hydroxylase activity. Active in the metabolic activation of hexamethylphosphoramide, N,N-dimethylaniline, 2'-methoxyacetophenone, N-nitrosomethylphenylamine, and the tobacco-specific carcinogen, 4-(methylnitrosamino)-1-(3-pyridyl)-1-butanone. Possesses phenacetin O-deethylation activity.
Synonyms: CPAD; CYP2A; CYPIIA13
Tractability: Small molecule: a structure with a bound ligand is known; it belongs to a druggable protein family. Antibody: UniProt places it where antibodies can reach, with medium confidence. PROTAC: a small molecule that binds it is known.
Target class: Cytochrome P450 family 2A; Enzyme; Cytochrome P450; Cytochrome P450 family 2
Safety:
Unwanted effects reported when the protein is acted on. In parentheses: how it was acted on, where the effect was seen, and who reports it.
nicotine dependence (source: ClinPGx)
Gene: Protein-coding gene on chromosome 19 (41,088,451 to 41,096,195, forward strand). Ensembl gene ENSG00000197838.
Subcellular location: Endoplasmic reticulum membrane; Microsome membrane
Pathways (Reactome):
Metabolism: Aflatoxin activation and detoxification; CYP2E1 reactions; Fatty acids; Xenobiotics
Gene Ontology:
Molecular function: heme binding; arachidonate epoxygenase activity; coumarin 7-hydroxylase activity; monooxygenase activity; oxidoreductase activity, acting on paired donors, with incorporation or reduction of molecular oxygen, reduced flavin or flavoprotein as one donor, and incorporation of one atom of oxygen; iron ion binding; oxidoreductase activity, acting on paired donors, with incorporation or reduction of molecular oxygen
Biological process: aflatoxin metabolic process; coumarin metabolic process; epoxygenase P450 pathway; xenobiotic metabolic process
Cellular component: cytoplasm; endoplasmic reticulum membrane
Genetic constraint (gnomAD): Loss-of-function variants: 31 observed, 42.26 expected, observed/expected ratio (o/e) 0.73, 90% interval 0.55 to 0.99. The upper end of that interval is the gene's LOEUF score, 0.99, which puts it in group 4 of 6, group 1 being the genes least tolerant of losing a copy. Missense variants: 731 observed, 660.84 expected, observed/expected ratio (o/e) 1.11, 90% interval 1.04 to 1.18. Synonymous variants: 269 observed, 262.36 expected, observed/expected ratio (o/e) 1.03, 90% interval 0.93 to 1.13.
Homologues: Orthologues: macaque CYP2A29 (94% identical), macaque CYP2A24 (93% identical), dog CYP2A13 (92% identical), macaque CYP2A23 (92% identical), pig CYP2A19 (90% identical), rat Cyp2a3 (89% identical), mouse Cyp2a5 (88% identical), rabbit CYP2A10 (88% identical), dog CYP2A7 (88% identical), mouse Cyp2a4 (87% identical), mouse Cyp2a12 (73% identical), mouse Cyp2a22 (73% identical), and 2 more. Paralogues in human: CYP2A6 (94% identical), CYP2A7 (91% identical), CYP2F1 (53% identical), CYP2B6 (52% identical), CYP2C19 (51% identical), CYP2C8 (50% identical), CYP2C18 (49% identical), CYP2C9 (49% identical), CYP2S1 (48% identical), CYP2E1 (47% identical), CYP2J2 (40% identical), CYP2U1 (38% identical), and 3 more.
Diseases named in the same sentence as CYP2A13 in open-access papers:
CYP2A13 is named in the same sentence as 17 diseases in open-access papers, as found by Europe PMC text mining. Sharing a sentence is not in itself a finding about the gene and the disease. The quoted sentences say what the papers report.
lung carcinoma (8 papers, 2017 to 2025). "Recently, the interaction between CYP2A13 and ABCB1was reported to be closely associated with lung cancer, and CYP2A13 was identified as a potential critical metabolic enzyme gene in the carcinogenesis of lung cancer." (PMID 34423049, 2021). "Odds ratio (OR) and 95% confidence interval (95% CI) were used to determine the effects of the CYP2A13 polymorphism on lung cancer risk, respectively." (PMID 33327254, 2020). "This meta-analysis will summarize the association between CYP2A13 polymorphisms and the risk of lung cancer." (PMID 33327254, 2020). "This systematic review will be the first to assess the association between CYP2A13 polymorphisms and the risk of lung cancer." (PMID 33327254, 2020). "PAHs in cigarette smoke, such as pyrene, 1-hydroxypyrene, 1-nitropyrene and 1-acetylpyrene, can be metabolically activated by CYP2A13 and are thought to be associated with lung cancer." (PMID 29027939, 2017). "It was concluded that this CYP2A13 genotype may contribute to individual susceptibility to early-onset lung cancer in women." (PMID 34830188, 2021). "Therefore, in this study, the meta-analysis method was used to systematically evaluate the relationship between CYP2A13 gene polymorphism and lung cancer susceptibility, in order to provide a basis for exploring clinical drug targets and cancer prevention." (PMID 33327254, 2020). "Therefore, the aim of this meta-analysis is to provide a precise conclusion on the potential association between CYP2A13 polymorphisms and the risk of lung cancer based on case-control studies." (PMID 33327254, 2020). "Thus, it was suggested that CYP1B1 and CYP2A13 genotypes may contribute to individual susceptibility to early-onset lung cancer in women." (PMID 34830188, 2021). "Recently, lung cancer has become the most common cause of cancer-related death, several studies indicate that the cytochrome P450 2A13 (CYP2A13) polymorphisms may be correlated with lung cancer susceptibility, but the results have been inconsistent and inconclusive." (PMID 33327254, 2020). "NNK is particularly considered important for the formation of human lung cancer and is metabolized more effectively to potentially carcinogenic intermediates by CYP2A13 instead of CYP2A6." (PMID 31998435, 2020). "The study aims to understand the role of CYP2A13 in the metabolic activation of toxic components of cigarettes and related respiratory diseases, including lung cancer." (PMID 29027939, 2017). "NNK is the most well-known carcinogen in cigarette smoke, and CYP2A13 was reported to play a key role in NNK-mediated lung cancer." (PMID 29027939, 2017). "Two other CYPs associated with lung cancer risk due to cigarette smoking, i.e., CYP2A6 and CYP2A13, displayed moderate up-regulation (FC of 9.5 and 8.9, respectively) in differentiated ALI-PBEC." (PMID 27738743, 2017). "In the metabolism of xenobiotics by cytochrome P450, nitrosamine 4‐(methylnitrosamino)‐1‐(3‐pyridyl)‐1‐butanone (NNK) was downregulated in the HFD group, though it was partially upregulated in the MPE group, consistent with the role of CYP2A13 in its activation in lung cancer." (PMID 40685922, 2025). "Interestingly, CYP2A13 is abundantly expressed in lung tissue and is considered a significant player in the tobacco-induced lung cancer process." (PMID 34830188, 2021). "Interestingly, there was little expression of the CYP2A13 protein in different types of human lung carcinomas." (PMID 34830188, 2021). "Interestingly, by using epigenetic agents (azacytidine—DNA demethylation agent and trichostatin A—histone deacetylation inhibitor), it was found that CYP2A13 expression is induced in NCI-H441 human lung cancer cells." (PMID 34830188, 2021).
lung carcinoma (continued). "Interestingly, women seem to be prone to an increased risk of early-onset lung cancer if they are carriers of the minor allele of CYP1B1 SNP rs1056836 (10042C>G/T), but a nonsignificant increased risk was observed for the carriers of the minor allele of CYP2A13 SNP rs1709084 (13103A>G)." (PMID 34830188, 2021). "This suggests that most smoking-related human lung cancers are bronchogenic and that the regulation of CYP2A13 expression is not altered in lung cancer cells." (PMID 34830188, 2021). "Nitrosamine 4-(methylnitrosamino)-1-(3-pyridyl)-1-butanone (NNK) is bioactivated in human lung cancer by CYP2A13." (PMID 31998435, 2020). "The dominant expression of CYP2A13 in human bronchial epithelium and its high efficiency in the metabolic activation of tobacco-specific carcinogenic NNK are consistent with observations that most smoking-related lung cancers are bronchogenic." (PMID 29027939, 2017). "Since the level of CYP2A13, but not CYP2A6, was correlated with lung microsomal NNK metabolic activity, it was speculated that people with relatively high levels of CYP2A13 expression are likely to have an increased risk of developing smoking-related lung cancer." (PMID 34830188, 2021).
lung adenocarcinoma (3 papers, 2012 to 2021). A carcinoma that arises from the lung and is characterized by the presence of malignant glandular epithelial cells. "A variant allele of CYP2A13 (CYP2A13*2) was previously found to be associated with a lower incidence of lung adenocarcinoma in smokers and was associated with a lower level of expression compared to the CYP2A13*1 allele." (PMID 34830188, 2021). "The reduction in lung adenocarcinoma has been associated with CYP2A13*2 genetic polymorphism given by C→T transition, leading to Arg257Cys substitution and reduced activity of CYP2A13 towards NNK." (PMID 34830188, 2021). "A stratification analysis demonstrated that the reduced risk of lung adenocarcinoma was related to the CYP2A13 variant and was limited to smokers, especially light smokers, but not non-smokers or heavy smokers." (PMID 34830188, 2021). "The significance of these differences are underscored by the variant CYP2A13*2, which is associated with decreased incidences of lung adenocarcinoma in smokers." (PMID 22375630, 2012). "In the study, where CYP2A13 expression was examined in non-small cell lung cancer (NSCLC) tissues, researchers observed the downregulation of CYP2A13 in lung adenocarcinoma." (PMID 34830188, 2021). "FABP1 was reported to correlate with non-alcoholic fatty liver disease, and CYP2A13 was found to be involved in the development and progression of lung adenocarcinoma; however, neither of them was previously associated with NSLN metastasis." (PMID 26311227, 2015).
bladder cancer (2 papers, 2019 to 2021). "However, the risk of bladder cancer was revealed recently for CYP2A13*1/*2 genotypes in Japanese smokers." (PMID 34830188, 2021). "Since smoking is the predominant risk factor for bladder cancer, the appropriate inhibition of CYP2A13 might stop the metabolism of some aromatic amines from smoke (e.g., 4-aminobiphenyl) that is metabolized by CYP2A13 into the ultimate carcinogens." (PMID 34830188, 2021). "Cytochrome P450 enzymes such as CYP2A7 and CYP2A13 score highly as well, and these genes are implicated in bladder cancer but not normally expressed in breast tissue." (PMID 31014259, 2019).
breast carcinoma (1 paper, 2025). "Breast cancer models, particularly MCF-7 cells, exhibited a different CYP450 profile, with CYP2J2, CYP2S1, CYP2A6 and CYP2A13 being the most prominent isoforms." (PMID 41174467, 2025). "In MCF-7 breast cancer cells, multiple CYP450 isoforms were identified, including CYP2A6, CYP2A13, and CYP2J2, albeit at lower sequence coverages ranging from 1% to 7%." (PMID 41174467, 2025).
head and neck cancer (1 paper, 2021). A primary or metastatic malignant neoplasm affecting the head and neck. "In a comparison of a group of 203 head and neck cancer patients, next to the 201 healthy controls, two novel polymorphisms of CYP2A13 (T478C and T494C) were detected that were associated with a significantly reduced risk of cancer." (PMID 34830188, 2021). "Another type of association of CYP2A13 polymorphism and head and neck cancer was observed in a cohort of North Indians." (PMID 34830188, 2021). "A significant interaction between smoking and the methylation status of CYP2A13 was observed, and it was suggested that the hypermethylation of CYP2A13 is independent from and in interaction with a smoking associated with an increased risk of head and neck cancer." (PMID 34830188, 2021). "This was studied for the CYP2A13 gene in head and neck cancer tissues." (PMID 34830188, 2021).
non-small cell lung carcinoma (1 paper, 2021). A group of at least three distinct histological types of lung cancer, including non-small cell squamous cell carcinoma, adenocarcinoma, and large cell carcinoma. "However, it was suggested that the high expression of CYP2A13 might be associated with tumor development and progression in non-small cell lung carcinomas." (PMID 34830188, 2021).
tyrosinemia (1 paper, 2019). An autosomal recessive inherited metabolic disorder caused by mutations in the FAH, HPD, and TAT genes. "The second metabolite associated with CYP2A13 was hydroxyphenyllactate, which is a tyrosine metabolite, and the L-form of it has been reported to be highly elevated in the urine of patients with pheylketonuria and tyrosinemia." (PMID 31113383, 2019).
cancer (3 papers, 2020 to 2025). A tumor composed of atypical neoplastic, often pleomorphic cells that invade other tissues. "On the contrary, the C578T mutant allele of CYP2A13 was found only in cancer patients." (PMID 34830188, 2021). "Therefore, it is of interest to monitor whether there is a correlation between certain CYP2A13 polymorphisms and the incidence of any type of cancer." (PMID 34830188, 2021). "If one or both of the respiratory enzymes CYP2A13 and CYP2F1 contribute to high-affinity-pathway two, then the reported associations of blood cancers with benzene exposures in ambient populations should take this into account." (PMID 40943470, 2025). "Some aspects of CYP2A13 expression regulation can be deduced from cancer cells." (PMID 34830188, 2021).
respiratory disorders (1 paper, 2017). "CYP2A13 was much more active during the metabolic activation of CSE-O in human lung epithelial cells, which suggests that CYP2A13 may be the primary metabolic enzyme involved in CSE-O metabolism in situ and possibly plays an important role in cigarette smoke-induced respiratory disorders." (PMID 29027939, 2017).
tumor (1 paper, 2021). "Interestingly, whereas CYP2A13 mRNA and protein were significantly reduced in NNK-treated groups, pro-inflammatory cytokines, such as TNFα, IFN-γ and IL-6, were significantly higher in the tumor-bearing mice." (PMID 34830188, 2021).
CYP2A13 also shares sentences with these, for which no sentence is quoted: asthma (2 papers); chronic obstructive pulmonary disease (1); ciliopathies (1); colorectal cancer (1); Granuloma (1); nicotine dependence (1); non-alcoholic fatty liver disease (1).